CDC42 (cell division cycle 42)
Diseases named in the same sentence as CDC42 in open-access papers (continued):
Sharing a sentence is not in itself a finding about the gene and the disease.
infection (continued). "To determine the mechanism controlling the contraction of HTMC cells after infection and to identify possible medication targets, we examined whether low molecular weight G proteins in the Rho family including Rho, Rac, and Cdc42, were activated." (PMID 40353220, 2025). "Notably, an increase in GTP-bound (active) forms of RhoA, Rac1 and Cdc42 was observed in WT cells after 1 h of infection; however, such activation was largely prevented in Egr-1-knockout cells." (PMID 38233877, 2024). "Thereupon, Rap1b, CDC42 cascade signaling, and Cofilin, the direct executor of cytoskeleton regulation, are likely to be potential host therapeutic targets for antiviral strategies during the early and lytic infection of HSV-1 in epithelial cells." (PMID 37515145, 2023). "The discrepancy suggested the possibility that Cdc42 may switch its preferred substrates between actin and vimentin, depending on specific pathogens, host cell types, and/or the time course of infection." (PMID 36717589, 2023). "Similarly, in human macrophages, infection with L. amazonensis, L. braziliensis or L. infantum resulted in reduced Rac1, Cdc42, and RhoA expression in a 3D environment compared to uninfected controls." (PMID 37576604, 2023). "However, we also identified reduced expression of Rac1 and Cdc42 following infection by all three Leishmania spp." (PMID 37576604, 2023). "When Cdc42 protein is knocked down or the ML-141 allosteric inhibitor is used, there is a significant decrease in infection, suggesting that Cdc42 may play a role in trafficking." (PMID 35746622, 2022). "HSV-1 shows similar reliance on Cdc42 for actin rearrangement during infection." (PMID 35746622, 2022). "Cdc42 is also involved in infection by T. annulata, a tick-borne apicomplexan infecting ruminants." (PMID 35889089, 2022). "Having shown that infection decreased in cells treated with Cdc42 siRNA, we investigated whether this change in infection was due to cell cycle arrest due to the loss of Cdc42 protein." (PMID 35746622, 2022). "The hypothesis was based on our earlier findings that 1.0 μM simvastatin decreases intracellular infection in part by sequestering host GTPases, including CDC42, the host-directed target of ML141." (PMID 33240647, 2020). "In this study, we show that EHV-1 activates the small GTPases Rac1 and Cdc42 during infection." (PMID 32645930, 2020). "As treatment with Vi inhibited invasion of epithelial cells with Salmonella, we analyzed whether incubation with this polysaccharide might alter the ability of these cells to activate Rac-1 and Cdc42 during infection with S. Typhimurium." (PMID 31134159, 2019). "Additionally, Rho GTPases, such as Cdc42, Rac1 and Rac2, regulate phagocytosis by altering hemocyte cell shape after infection." (PMID 30518379, 2018). "Cdc42 and RacA derivatives were used in the following complementation analyses to investigate the importance of Cdc42-BemA and RacA-NoxR interactions in hyphal growth, ROS production and symbiotic infection by E. festucae in the host plant." (PMID 29370294, 2018). "To test the hypothesis that migration inhibition by LAI-1 or L. pneumophila converges on common host factors, we depleted the small GTPases Cdc42 or Rac1 in A549 cells prior to an infection with wild-type or ΔicmT mutant L. pneumophila." (PMID 26633832, 2015). "To assess whether the effect of ATF4 knockdown on Cdc42 occurs at the transcriptional level, we measured Cdc42 transcript levels by q-PCR at various times after infection with control and shATF4 lentivirus." (PMID 25071442, 2014). "For validation of outlined interactions and to legitimate calculated miR-29a-target interactions and to prove biological significance, we examined the expression of miR-29a, AKT3, BAIAP2, COL4A1, VCL, CAV2 and CDC42 over the course of infection by means of RT-qPCRs." (PMID 23826261, 2013).
infection (continued). "Furthermore, using the CRIB domains of PAK and WASP that bind activated Rac-1 and Cdc42, respectively, we demonstrate that EspT activates both Rac-1 and Cdc42 during infection of Swiss 3T3 cells." (PMID 19016787, 2009). "Consistent with this, inhibition of the Cdc42 pathway blocked filopodia formation and led to widespread pedestals at early time points post infection while eliminating Nck, which links Tir to the actin cytoskeleton, blocked pedestal formation and promoted a long-term presence of filopodia." (PMID 19046338, 2009). "This ‘feed-forward’ amplification and evolved effector interdependency may allow the Cdc42/Rac1-dependent pathway to dominate during WT infection." (PMID 18389058, 2008). "Whether Cdc42 downregulation impairs the expression of APH0032 exclusively or other unidentified AVM-localized A. phagocytophilum effectors that are coincidentally expressed with APH0032 during the infection cycle is unknown." (PMID 38415594, 2024). "We observed upregulation of Cdc42 expression post-infection with SARS-CoV-2 Omicron BA.4 or following spike protein stimulation, indicating that the spike protein induces senescence in alveolar epithelial cells in mice, and Cdc42 may be involved in this process." (PMID 39559701, 2024). "However, since prion steady-state levels in persistently infected cells are highly dependent on functional dynamins and Cdc42, we further explored whether infection of cells can be inhibited by transcriptional silencing of dynamin and Cdc42, respectively." (PMID 38102121, 2023). "Thus, the lethal phenotype of the Cdc42 KO mice was most likely due to infection and dehydration." (PMID 31410202, 2019). "Symbiotic defects found in the racA mutant were rescued by introduction of a Cdc42 with key amino acids substitutions crucial for RacA function, highlighting the significance of the specific interactions of these GTPases with BemA and NoxR for their functional differentiation in symbiotic infection." (PMID 29370294, 2018). "In analogy to what happens in pathogenic fungi during an infection event, communication events with its host plants can occur also in T. borchii, leading in both partners to a coordinated program of gene expression, probably activated by a MAP kinase cascade controlled by Cdc42." (PMID 18400087, 2008). "Similar to the CDC42 GTPase group, viruses were the most common agents, exhibiting a greater frequency of Epstein–Barr virus (EBV) (29.4%) and HPV (17.2%) infection." (PMID 40860338, 2025). "Western blotting analysisrevealed that the activities of Cdc42-GTPase and Rac1-GTPase were transientlyinduced by PEDV during the initial phases of infection at 30 min." (PMID 40094365, 2025). "It is likely that the precise level of Cdc42/N-WASP activity required to prevent pathogen uptake, and the time taken to achieve this level during infection will vary between different cell types and/or culture conditions." (PMID 37168569, 2023). "SARS-CoV-2 infection resulted in a significant overexpression of Notch1, Notch2, CTNNB1, CDC42, and PSEN1 after 24 h of infection." (PMID 37211584, 2023). "Post infection, Salmonella utilizes the N-terminal of T3SS effector SopB to bind and activate host Cdc42 GTPase, and subsequently promotes the phosphorylation of host MEK1/2." (PMID 36717589, 2023). "Rac1 and Cdc42 G-LISA kits were used to determine the amount of active (GTP bound) Rac1 and Cdc42 present in the cells after infection." (PMID 33637714, 2021). "The infection of EHV-1 was significantly reduced in cells treated with Rac1 (~60%) and Cdc42 inhibitors (~40%)." (PMID 32645930, 2020). "Since the NPFs N-WASP and WAVE bridge the activated Rho-family GTPases Cdc42 and Rac1 to the Arp2/3 complex, respectively, we next examined the recruitment of N-WASP and the WAVE complex following C. trachomatis LGV2 infection of RPE1 cells." (PMID 29727463, 2018).
infection (continued). "TGEV acts via the EGFR-PI3 K-Rac1/Cdc42-PAK-LIMK signaling pathway to regulate coflin activity and F-actin arrangement early in infection, and promotes TGEV entry." (PMID 30236161, 2018). "The endocytic process (membrane ruffling) mediated by beta integrins (e.g., CDC42 and RAC1) was mildly increased at T3h, but inhibited T24h after infection." (PMID 28491823, 2017). "Of note, infection of PCa cells with Lenti-141 at low MOI (that is, 2.5 and 5) also decreased the Rho GTPase activities of both RAC1 and CDC42." (PMID 28112170, 2017). "For example, it has been known that infection with influenza virus significantly down regulates the ARHGAP21, an inhibitor of Cdc42 activation and thereby activates Cdc42 signaling in infected cells." (PMID 26206138, 2015). "At different time points following HeLa cell infection with S. meliloti, lysates were prepared and the amount of active, GTP-bound, Cdc42, Rac1 and RhoA precipitated with the GST-CRIB fusion protein was determined by western blotting." (PMID 23409119, 2013). "twofold increase in the level of Cdc42-GTP at 15 and 30 min post infection compared with uninfected cells." (PMID 19046338, 2009). "Interestingly, several pathways were significantly increased in peripheral blood granulocytes compared with cells that had invaded the infection site, including WNT signaling, Rho and Cdc42 GTPases, G protein–mediated events, and IFN-α response." (PMID 38421730, 2024). "To investigate whether infection of other bacterial species can manipulate CDC42 K153 acetylation, we infected HEK293T cells overexpressing Flag-CDC42 with several enteropathogenic and probiotic bacteria." (PMID 36812247, 2023). "In our previous study, we showed that infection-positive acinar cells lacking Cdc42 in an adenovirus vector-based system have disrupted apical membranes in their SGs." (PMID 38139048, 2023). "Infection of cells with WT but not ΔsopE2 S. Tm resulted in a substantial increase in N-WASP binding to Cdc42, indicative of SopE2-dependent N-WASP activation." (PMID 37168569, 2023). "siRNA directed at Cdc42 GTPase resulted in a statistically significant reduction of infection and a corresponding lack of filopodia induction." (PMID 35746622, 2022). "We found that there was nearly no activation of either Rac1 and Cdc42 in the IQGAP1 knockdown cells, while there was robust activation of both Rac1 and Cdc42 in the cells expressing the non-targeting shRNA during infection." (PMID 33637714, 2021). "Furthermore, infection with WR Vaccinia virus is highly dependent on Rac1, whereas infection with IHD-J is highly dependent on Cdc42, highlighting the existence of different pathways of macropinocytosis that can be exploited by viruses." (PMID 32756454, 2020). "The Rac1 and Cdc42 signaling is presumably orthogonal to Ca2+ release, since Rac1 and Cdc42 inhibitors affected the infection of both EHV-1 and EHV-4, which do not bind to integrins." (PMID 32645930, 2020). "This was suggested from a GTPase pulldown assay showing that active RhoA and Cdc42 were no longer detected in ZJO-infected cell lysates after 1 h of infection, even if they were stimulated with the nonhydrolyzable GTP analogue GTPγS." (PMID 29252102, 2018). "Importantly, infection of Caco-2 BBE1 cells with wild-type Listeria alters tight junctions similarly to inhibition of Tuba, N-WASP, or Cdc42." (PMID 24600591, 2014). "As Cdc42 is important for adhesion and fluid-phase endocytosis, Cln3−/− mice and JNCL patients may display BBB dysregulation when stressed, such as during an infection or as neurons succumb to disease." (PMID 24792215, 2014). "While Cdc42 protein decreased along with the duration of infection, there was no significant change in Cdc42 mRNA levels in cortical or hippocampal (data not shown) neurons after ATF4 knockdown." (PMID 25071442, 2014).
infection (continued). "However, when we infected Cdc42 expressing cells with vaccinia virus (IHD-J/GFP), which enters cells by macropinocytosis, the DN mutant blocked infection by about 50%." (PMID 22536154, 2012). "In contrast, no detectable Cdc42 activation and host cell invasion was found in cells infected with ΔflaA/B or ΔflhA mutants during the entire course of infection." (PMID 22204307, 2011). "While growing levels of activated Cdc42 were detected in FAK-positive cells over time with wt C. jejuni, no detectable activation of Cdc42 was found in FAK-/- cells during the entire course of infection." (PMID 22204307, 2011). "However, infection with L. infantum, but not with L. amazonensis or L. braziliensis, led to increased Rac1, Cdc42, and RhoA expression compared to uninfected controls in a 3D environment." (PMID 37576604, 2023). "We still saw infection and overlap of virus with EEA1 after ML-141 inhibition of Cdc42 and siRNA targeted treatments, albeit significantly decreased, which suggests that Cdc42 may not be essential for viral entry into cells but potentially in viral trafficking." (PMID 35746622, 2022). "In a three-hour infection assay, we observed a significant reduction of EHV-1, which binds to α4β1 integrins, as well as EHV-1 gH4 or EHV-1 gHS440A (these two viruses cannot bind to α4β1-integrin) infections after treatment of cells with Rac1 and Cdc42 inhibitors." (PMID 32645930, 2020). "Interestingly, knocking down CDC42 or ARF6 suppressed luciferase expression after infection with ANDV pseudovirions, though not with wild-type ANDV virus." (PMID 27780263, 2016). "In addition, Cdc42, PAK1, and N-Wasp were required for RSV internalization and infection." (PMID 23593008, 2013). "Since we could not detect the activation of endogenous Cdc42 triggered by infection with V. parahaemolyticus using a pull-down assay, the amounts of active Cdc42 in infected BMMs were quantified by loading with GTP-γS followed by a pull-down assay." (PMID 23357873, 2013). "As the activation of endogenous Cdc42 is not observed upon infection with V. parahaemolyticus, we speculate that the basal activity of small GTPases is sufficient for maintaining the speck formation." (PMID 23357873, 2013). "Indeed, FAK autophosphorylation is strongly activated by C. jejuni and pharmacological inhibition of FAK as well as infection of FAK-/- cells did not lead to stimulation of Cdc42 GTPase activity." (PMID 22204307, 2011). "We further demonstrated that infection of wild-type cells induces increasing amounts of phosphorylated FAK and growth factor receptors (EGFR and PDGFR) during the course of infection, correlating with accumulating Cdc42-GTP levels and C. jejuni invasion over time." (PMID 22204307, 2011). "No Cdc42 activation was seen in cells infected with E2348/60Δmap 15 min post infection." (PMID 19046338, 2009). "Infection of transfected cells with E2348/69 expressing EspM2 or EspM3 for 1.5 h revealed that formation of GP-SF and LR-SF, respectively, was not affected by inactivation of Cdc42 or Rac1." (PMID 18331467, 2008). "Thus, while Cdc42 downregulation does not inhibit A. phagocytophilum replication, it reduces TGN anterograde traffic into the ApV, which is linked to an inhibition in ApV maturation and hence progression of the pathogen’s infection cycle." (PMID 38415594, 2024). "Interestingly however, both the ΔsopE1 and ΔsopE1/E2 strains invade to a similar extent in the presence of SMIFH2, indicating that in the absence of SopE1 at least, SopE2 activation of Cdc42 can promote invasion in a formin-dependent manner at early stages of an infection." (PMID 37168569, 2023). "Using GST-pulldown based assays we could demonstrate that infection with EPEC-wt, but not with EPEC-escV (escV::Tn5kan; T3SS deficient), or EPEC-∆espH, decreased the Cdc42 and Rac1 activity levels in the infected cells, suggesting that EspH is the effector that suppresses the RhoGTPases." (PMID 36219160, 2022).
infection (continued). "Activation of Rac1 by HIV signaling has been previously reported; however activation of Cdc42 by HIV-1 signaling in CD4 T cells and its role in promoting infection has not previously been demonstrated." (PMID 28114951, 2017). "Although other strains expressing only SopE2, which acts on Cdc42, could efface MV and induce RA, they failed to abrogate this cellular function in the PEC infection model." (PMID 38894970, 2024). "Interestingly, knocking down macropinocytosis markers PAK-1, CDC42, and ARF6 did not significantly reduce ANDV infection." (PMID 27780263, 2016). "Of those tested Cdc42ep3 (CDC42 effector protein), ARHGDIB (Rho GDP dissociation inhibitor (GDI) beta), Acta2 (Alpha actin 2), Egr2 (Early growth response 2), IL-6 (Interleukin 6) and Vav3 (vav 1 guanine nucleotide exchange factor), were induced by EPEC infection but not by infection with EPEC Δtir." (PMID 21490959, 2011).
immunodeficiency (6 papers, 2020 to 2025). Failure of the immune system to protect the body adequately from infection, due to the absence or insufficiency of some component process or substance. "Fourthly, limited study reported the clinical value of CDC42 in immune diseases; thus, more attention should be paid to explore the correlation of CDC42 with disease risk and activity in patients with immune diseases." (PMID 34859333, 2022). "Here, the upregulation of CDC42 and LAMTOR5 expression may be correlated with immune dysfunctions of the airways caused by ammonia exposure." (PMID 37250049, 2023).
neurodegenerative disease (6 papers, 2014 to 2022). A disorder of the central nervous system characterized by gradual and progressive loss of neural tissue and neurologic function. "Due to the role of cdc42 in preventing neurodegenerative diseases and also development and maintenance of LTP, overexpression of this protein has been suggested as a treatment for preventing neurodegeneration." (PMID 31053743, 2019). "As drugs are being developed for other GTPases, ARF1 or Cdc42 are potentially suitable targets for therapeutic development for JNCL, a currently untreatable, fatal neurodegenerative disease." (PMID 24792215, 2014). "Therefore, it will be interesting to see how the two forms of CDC42 affect the expression and/or activation levels of mTOR and the EGFR in adult brains and whether the deregulation of these CDC42 splice variants is involved in the pathogenesis responsible for neurodegenerative diseases." (PMID 36206843, 2022).
adenocarcinoma (4 papers, 2016 to 2021). A common cancer characterized by the presence of malignant glandular cells. "In the current study, IHC was used to examine Cdc42 distribution in 359 cases of well and moderately differentiated adenocarcinoma." (PMID 32139668, 2020). "This in vitro model consists on cell clones with the stable expression of the wild type form of CDC42 as well as the genetic interference of CDC42 expression by shRNA in the adenocarcinoma colorectal cell line SW620." (PMID 28460460, 2017). "Depletion of the actin regulator N-WASP, a direct effector of Cdc42, and depletion of Cdc42 have similar effects on invadopodia formation in cultured rat mammary MTln3 adenocarcinoma cells." (PMID 26765257, 2016). "Although many cells in the poorly differentiated adenocarcinoma tissue sections showed polarised Cdc42 expression, no intact glands were available for referencing directionality, we excluded these cases for further analyses." (PMID 32139668, 2020).